DACT1 (dishevelled binding antagonist of beta catenin 1)
Diseases named in the same sentence as DACT1 in open-access papers (continued):
Sharing a sentence is not in itself a finding about the gene and the disease.
colon carcinoma (continued). "The levels of DACT1 and β-catenin in colon cancer cell lines were correlated." (PMID 22470507, 2012). "It was found that DACT1 increased the nuclear and cytoplasmic fractions of β-catenin via phosphorylated GSK-3β at Ser9 to promote cell proliferation in colon cancer." (PMID 35864965, 2022). "Conversely, cellular proliferation decreased when endogenous DACT1 expression was silenced by stable transfection with siRNA vectors that targeted DACT1 in the HCT116, LoVo and HT29 colon cancer cell lines, which have much higher endogenous levels of DACT1." (PMID 22470507, 2012). "Following transfection with a DACT1 cDNA expression construct, SW480 colon cancer cells, which express very low endogenous levels of DACT1, demonstrated a significant increase in cellular proliferation." (PMID 22470507, 2012). "Similar to DACT1, ectopic expression of DACT2 led to a significant increase of apoptotic cells 15, 16, 91, induction on the expression of Bax in glioma cells 16, and the enhanced cleavage of PARP in colon cancer cells." (PMID 35864965, 2022). "DACT1 was frequently downregulated by promoter methylation in HCC, whereas another DACT family member, DACT3, was repressed by bivalent histone modifications in colon cancer." (PMID 23497530, 2013). "We found that DACT1 binds to axin and GSK-3β in colon cancer cells." (PMID 22470507, 2012). "Bioinformatic analyses have revealed that DACT1 mRNA is expressed in the amnion, fetal brain, eye, heart, adult brain medulla, gastric cancer (signet ring cell features), RER+ colon tumor, acute lymphoblastic leukemia, germ cell tumor, chondrosarcoma, and parathyroid tumors." (PMID 22470507, 2012).
cervical cancer (6 papers, 2020 to 2025). A primary or metastatic malignant neoplasm involving the cervix. "For example, the lncRNA H1FX-AS1 has been shown to induce apoptosis by sponging hsa-miR-324-3p to upregulate the level of DACT1 expression in cervical cancer." (PMID 36434735, 2022). "Taken together, KDM1A enhances the proliferation and migration of cervical cancer cells through regulating the expression of DACT1." (PMID 34350095, 2021). "This study is aimed at exploring the mechanism behind the KDM1A regulation on DACT1 in cervical cancer cells." (PMID 34350095, 2021). "The expression levels of KDM1A and DACT1 in cervical cancer cell lines were determined by qRT-PCR and western blot." (PMID 34350095, 2021). "More importantly, we further explored the mechanism of KDM1A regulation on DACT1 in cervical cancer." (PMID 34350095, 2021). "In vitro experiments verified the effect of KDM1A and DACT1 on proliferation and migration ability of cervical cancer cell lines after cell transfection." (PMID 34350095, 2021). "KDM1A can lead to histone 3 deacetylation, which consequently represses the expression of DACT1 in cervical cancer cells." (PMID 34350095, 2021). "qRT-PCR and western blot demonstrated that compared with H8 cells, the mRNA (p < 0.01) and protein (p < 0.01) expressions of KDM1A were elevated, while those of DACT1 were decreased (p < 0.01) in all cervical cancer cell lines." (PMID 34350095, 2021). "The novelty of this study was KDM1A-mediated histone 3 deacetylation on regulation of DACT1 in cervical cancer." (PMID 34350095, 2021). "In this study, we demonstrated the increased expression level of KDM1A and decreased expression level of DACT1 in both cervical cancer tissues (from TCGA database) and cervical cell lines." (PMID 34350095, 2021). "KDM1A can downregulate DACT1 expression through histone deacetylation and therefore suppress the proliferation and migration of cervical cancer cells." (PMID 34350095, 2021). "In summary, results in this study showed that KDM1A was highly expressed while DACT1 was lowly expressed in cervical cancer tissues and cells." (PMID 34350095, 2021). "The collected evidence showed that KDM1A in cervical cancer cells can suppress the expression of DACT1 through histone 3 deacetylation and therefore enhance the progression of this disease." (PMID 34350095, 2021). "Similar with a previous study, the results in this study demonstrated that overexpression of DACT1 can attenuate the progression of cervical cancer, highlighting the tumor suppressing role of DACT1 in cervical cancer." (PMID 34350095, 2021). "Thereafter, we measured the mRNA and protein expression levels of KDM1A and DACT1 in cervical cancer cell lines (HeLa, Ca Ski, SiHa, and C-33A) and immortalized human cervical epithelial cell line H8." (PMID 34350095, 2021). "Further exploration on KDM1A regulation on biological function of cervical cancer cells in this study showed that KDM1A can induce histone 3 deacetylation so as to suppress the expression of DACT1." (PMID 34350095, 2021). "Increased expression of KDM1A and decreased expression of DACT1 in cervical cancer cells were noticed in a previous study." (PMID 34350095, 2021). "In light of recent studies, overexpression of DACT1 was reported to suppress the proliferation, invasion, and migration ability of cervical cancer cells." (PMID 34350095, 2021). "KDM1A could downregulate DACT1 expression through histone deacetylation to enhance the proliferation of cervical cancer cells." (PMID 35864965, 2022). "The expression profile of KDM1A and DACT1 in cervical cancer tissues was searched in TCGA database." (PMID 34350095, 2021). "Therefore, KDM1A enhances the progression of cervical cancer by inducing histone 3 deacetylation and downregulating DACT1 expression." (PMID 34350095, 2021). "However, lncRNA H1FX-AS1 modulates miR-324-3p-mediated inhibition of DACT1 in cervical cancer." (PMID 35864965, 2022).
cervical cancer (continued). "Therefore, KDM1A may be able to regulate DACT1 expression through histone 3 deacetylation in cervical cancer cell lines." (PMID 34350095, 2021). "The measurement on cell proliferation and migration ability showed that overexpression of DACT1 could suppress cell proliferation and migration of cervical cancer cells, while overexpression of KDM1A could abolish DACT1-mediated suppression on cervical cancer cells." (PMID 34350095, 2021). "Therefore, this study was performed to verify whether KDM1A can regulate DACT1 expression to regulate biological functions of cervical cancer cells." (PMID 34350095, 2021). "Therefore, we speculated that KDM1A may be able to downregulate DACT1 expression through histone deacetylation, to enhance the proliferation and migration of cervical cancer cells." (PMID 34350095, 2021). "Further investigation in cervical cancer cell lines confirmed the highly expressed profile of KDM1A in cervical cell lines and also identified DACT1 as a target gene of KDM1A." (PMID 34350095, 2021). "To further identify the possible interaction between KDM1A and DACT1 in cervical cancer cell lines, we then cotransfected overexpression of KDM1A and DACT1 in cervical cancer cell lines." (PMID 34350095, 2021). "TCGA database showed that cervical cancer tissues had elevated expression of KDM1A and decreased expression of DACT1, which was consistent with the observation in cervical cancer cell lines." (PMID 34350095, 2021).
esophageal squamous cell carcinoma (5 papers, 2017 to 2022). Esophageal squamous cell carcinoma (ESCC) is a type of esophageal carcinoma (EC) that can affect any part of the esophagus, but is usually located in the upper or middle third. "DACT1 belongs to the DACT (Disheveled-associated antagonist of β-catenin) family and is a methylation biomarker for DACT1 in esophageal squamous cell carcinoma." (PMID 36591507, 2022). "The tumor suppressive role of DACT1 can be also found in other malignant tumors, including type I ovarian cancer, leukemia cells, and esophageal squamous cell carcinoma." (PMID 34350095, 2021).
non-small cell lung carcinoma (5 papers, 2016 to 2022). A group of at least three distinct histological types of lung cancer, including non-small cell squamous cell carcinoma, adenocarcinoma, and large cell carcinoma. "Dysregulated DACT1 was associated with poor prognosis in non-small cell lung cancer patients." (PMID 27708215, 2016).
osteosarcoma (5 papers, 2023 to 2025). A usually aggressive malignant bone-forming mesenchymal neoplasm, predominantly affecting adolescents and young adults. "In the progression of osteosarcoma, the expression of DACT1 is regulated by the FTO-mediated m6A methylation modification." (PMID 40356725, 2025). "For example, in osteosarcoma, FTO demethylates m6A modifications, reducing the stability of DACT1 mRNA, thereby decreasing DACT1 expression and subsequently activating the Wnt signaling pathway." (PMID 39849461, 2025).
nasopharyngeal carcinoma (3 papers, 2019 to 2023). A carcinoma arising from the nasopharyngeal epithelium. "CNE2 cells were treated with 5-aza-2-deoxycytidine, and the variation in the methylation status of the DACT1 gene was detected, as well as the influence of methylation on invasiveness of nasopharyngeal carcinoma cells." (PMID 31182157, 2019). "The DACT1 gene was hyper-methylated in 32 of 38 cases of nasopharyngeal carcinoma with lymph node metastasis, and the DACT1 gene was hyper-methylated in 7 of 24 cases of nasopharyngeal carcinoma without lymph node metastasis." (PMID 31182157, 2019). "The purpose of the present study was to investigate the role of the methylation status of the DACT1 gene on the invasion and metastasis of nasopharyngeal carcinoma cells." (PMID 31182157, 2019). "The levels of methylation and expression of the DACT1 gene in nasopharyngeal carcinoma tissues and CNE2 cells were determined by methylation-specific PCR and RT-PCR, respectively." (PMID 31182157, 2019). "High expression of the DACT1 may have been invasive and metastatic in nasopharyngeal carcinoma cells." (PMID 38228050, 2023). "The DACT1 gene was hyper-methylated in 44 of 62 cases of nasopharyngeal carcinoma." (PMID 31182157, 2019). "Evidence in nasopharyngeal carcinoma showed that DACT1 expression levels in patients with nasopharyngeal carcinoma were closely related to the methylation condition and unregulated expression of DACT1 may be able to suppress the malignant expansion of nasopharyngeal carcinoma cells." (PMID 34350095, 2021). "High expression of DACT1 may inhibit the invasion and metastasis of nasopharyngeal carcinoma cells." (PMID 31182157, 2019). "The DACT1 mRNA level was weakly expressed or not expressed in all nasopharyngeal carcinoma tissues with hyper-methylated DACT1 genes; however, the DACT1 mRNA level was highly expressed in nasopharyngeal carcinoma tissues with low expression of the methylated DACT1 gene." (PMID 31182157, 2019).
atrial fibrillation (2 papers, 2019 to 2022). A disorder characterized by an electrocardiographic finding of a supraventricular arrhythmia characterized by the replacement of consistent P waves by rapid oscillations or fibrillatory waves that vary in size, shape and timing and are accompanied by an irregular ventricular response. "Having previously demonstrated that DACT1 was involved in atrial fibrillation by regulating the reorganization of connexin 43 and β-catenin, little is albeit known about DACT1 in human normal myocardial cells due to a lack of suitable research models." (PMID 35510412, 2022). "Previously, we demonstrated that the disheveled binding antagonist of β-catenin 1 (DACT1) was involved in atrial fibrillation by regulating the reorganization of connexin 43 and β-catenin in cardiomyocytes." (PMID 35510412, 2022). "While our previous study showed that DACT1 could regulate connexin 43 via cytoskeletal organization induced by β-catenin accumulation in cardiomyocytes of atrial fibrillation patients, in this study we analyzed their colocalization in CMs to further investigate their association." (PMID 35510412, 2022).
bladder cancer (2 papers, 2012 to 2022). "In the present study, we first examined the hypermethylation status of DACT1 in normal and bladder cancer tissue, as well as the levels of DACT1 mRNA transcripts and protein." (PMID 23554767, 2012). "DACT1 protein was detected in some bladder cancers, but at a significantly reduced level in comparison to normal controls." (PMID 23554767, 2012). "The methylation-specific PCR results showed that the DACT1 gene was mostly methylated in bladder cancer tissues." (PMID 23554767, 2012). "Western blot analysis showed that DACT1 expression is lower in bladder cancer and the trend was the same as the hypermethylation status of the DACT1 gene." (PMID 23554767, 2012). "DACT1 gene hypermethylation was closely associated with tumor size, grade and stage (P < 0.05), but not gender and age, suggesting that the methylation rate of the DACT1 gene increased with the progression of bladder cancer." (PMID 23554767, 2012). "Together with the fact that methylation of the DACT1 CpG island is common in bladder cancer, these findings indicate that DACT1 hypermethylation is related to the progression of bladder transitional cell carcinomas." (PMID 23554767, 2012). "In addition, methylation of the DACT1 CpG island is common in bladder cancer, repressing DACT1 expression." (PMID 35864965, 2022). "DACT1 was hypermethylated in almost all human bladder cancers but unmethylated in normal tissues." (PMID 23554767, 2012). "DACT1 mRNA expression was absent in most bladder carcinomas, but present in almost all normal bladder tissue." (PMID 23554767, 2012). "Western blot analysis confirmed that DACT1 protein was absent in bladder cancer tissues." (PMID 23554767, 2012).
bladder transitional cell carcinoma (2 papers, 2012 to 2022). The most common morphologic subtype of urinary bladder carcinoma (over 90% of cases). "Our results indicate that silencing and downregulation of DACT1 mRNA may be implicated in carcinogenesis and the progression of bladder urothelial carcinoma, and may be a potential prognostic factor." (PMID 23554767, 2012). "The purpose of this study was to determine the relationship between hypermethylation of DACT1 gene promoter and lower mRNA expression in bladder urothelial carcinoma tissue." (PMID 23554767, 2012). "Correlation between methylation status of the DACT1 gene and clinicopathological characteristics in bladder urothelial carcinoma patients." (PMID 23554767, 2012). "Using methylation-specific polymerase chain reaction (MSP) and reverse transcription polymerase chain reaction (RT-PCR), a clear relationship was found between hypermethylation status and the low expression of DACT1 in bladder transitional cell carcinomas." (PMID 23554767, 2012). "In this study, the methylation status of the DACT1 gene was examined in tissue from 29 normal bladders and tissue from 29 bladder urothelial carcinomas." (PMID 23554767, 2012). "In conclusion, our study showed that hypermthylation could regulate DACT1 expression in bladder transitional cell carcinomas." (PMID 23554767, 2012). "Better understanding of the mechanism of DACT1 expression may eventually lead to novel treatment for bladder transitional cell carcinomas." (PMID 23554767, 2012). "However, up to now, the role of DACT1 in bladder urothelial carcinoma has not yet been reported and whether DNA methylation participates in bladder carcinogenesis is also unclear." (PMID 23554767, 2012).
breast tumors (2 papers, 2013 to 2017). "Functional assays showed that ectopic expression of DACT1 could inhibit breast tumor cell proliferation in vivo and in vitro through inducing apoptosis, and further suppress tumor cell migration through antagonizing the Wnt/β-catenin signaling pathway." (PMID 23497530, 2013). "DACT1 expression in primary breast tumors was further examined at the RNA and protein levels." (PMID 23497530, 2013). "DACT1 is methylated in 29.9% of primary breast tumors, but not in surgical-margin tissues and normal breast tissues." (PMID 23497530, 2013).
hydronephrosis (2 papers, 2023 to 2024). Collection of urine in the renal pelvis that results in dilatation of the renal pelvis and calyces. "Kidney malformations in Dact1-deficient mice included fused kidneys, unilateral or bilateral kidney agenesis, cystic kidneys, and hydronephrosis, the ureters were blind-ended." (PMID 36066768, 2023). "Kidney ultrasound is warranted in patients carrying rare DACT1 variants since two-thirds of families described so far present with kidney agenesis, duplex/fused or (multi)cystic (hypo)dysplastic kidneys with hydronephrosis." (PMID 36066768, 2023). "Patients carrying DACT1 variants presented with kidney agenesis, duplex or (multi)cystic (hypo)dysplastic kidneys with hydronephrosis and TBS2 features." (PMID 36066768, 2023). "The similarity in TSHZ3 and DACT1 expression in the kidney and ureter is paralleled by a comparable CAKUT phenotype in carriers of TSHZ3 and DACT1 variants, i.e., MCDK or cystic kidney dysplasia, hydronephrosis and/or hydroureter." (PMID 39420202, 2024).
lung carcinoma (2 papers, 2012 to 2025). "A recent report identified a correlation between DACT1 expression in lung cancer and poor histological grade, large tumor size, extent of tumor invasion, and lymph node metastasis." (PMID 22470507, 2012).
mucinous ovarian cancer (2 papers, 2017 to 2020). An invasive malignant neoplasm that arises from the ovary and is characterized by the presence of malignant epithelial cells that contain intracytoplasmic mucin and may resemble the epithelial cells of the endocervix or gastrointestinal tract. "To elucidate the function of DACT1 in mEOC, we examined the effect of DACT1 expression on the growth characteristics of mucinous ovarian cancer cells using colony formation and growth curve assays." (PMID 28839145, 2017). "We found that expression of DACT1 was lower in EOC cell lines than normal ovarian tissues, and further that DACT1 expression was significantly lower in type I EOC cell lines, which include 3AO, a mEOC cell line arising from a patient with primary mucinous ovarian cancer." (PMID 28839145, 2017).
spina bifida (2 papers, 2014 to 2021). A congenital neural tube defect in which vertebrae are not fully formed. "It was demonstrated in mice that homozygous PCP mutations caused craniochisichisis, as shown for Vangl2, Celsr1, and Ptk7 while double heterozygosity for a PCP mutation and non-PCP mutation can cause spina bifida, as shown for Vangl2/Dact1 double heterozygotes." (PMID 24632739, 2014).
anal atresia (1 paper, 2023). "Dact1-deficient mice and patients carrying DACT1 variants show developmental defects that belong to the caudal regression syndrome including caudal vertebrae agenesis, anal atresia, kidney malformations, aberrantly ending ureters, bladder agenesis, and genital anomalies." (PMID 36066768, 2023).
colon adenocarcinoma (1 paper, 2012). "Our studies have also revealed that β-catenin and Dvl-2 are upregulated along with DACT1, and demonstrate that there is a trend toward poor survival in patients with tumors that have higher scores for DACT1 expression in colon adenocarcinomas." (PMID 22470507, 2012). "This demonstrates that there is a trend toward poor survival in patients with tumors that have higher scores for DACT1 expression in colon adenocarcinomas." (PMID 22470507, 2012). "Our studies have shown that DACT1 is overexpressed in human colonic adenocarcinomas." (PMID 22470507, 2012).
cortical atrophy (1 paper, 2023). "Therefore, we advise to focus on the DACT1 gene while exploring the genetic basis of cortical atrophy in AD patients." (PMID 38135866, 2023).
cyst (1 paper, 2023). A sac-like closed membranous structure that may be empty or contain fluid or amorphous material. "Except for bilateral kidney agenesis, all of these CAKUT phenotypes were also detected in our patients carrying DACT1 variants, particularly frequently cystic dysplastic kidneys (comprising MCDK, cystic kidney dysplasia, and kidney hypoplasia with a single cyst)." (PMID 36066768, 2023).